CXCL12 (C-X-C motif chemokine ligand 12)
Diseases named in the same sentence as CXCL12 in open-access papers (continued):
Sharing a sentence is not in itself a finding about the gene and the disease.
intracerebral hemorrhage (2 papers, 2023). A cerebrovascular disorder characterized by bleeding into one or both cerebral hemispheres including the basal ganglia and the cerebral cortex. "CXCL12 signals through CXCR4 and plays a critical role in angiogenesis in experimental intracerebral hemorrhage." (PMID 37817190, 2023).
limb ischemia (2 papers, 2012 to 2019). A ischemia that involves the limb. "As previously reported when CXCL12 is overexpressed in models of limb ischemia, it supports neoangiogenesis by attracting EPCs and by increasing the number of newly formed vessels leading to an increase in blood flow." (PMID 31533830, 2019). "More specifically, the disruption of the CXCL12/GAG interaction also leads to a defect in angiogenesis and neovascularisation in a limb ischemia model, which can be rescued by the administration of exogenous CXCL12γ." (PMID 31533830, 2019).
Lyme disease (2 papers, 2018 to 2023). Lyme disease (named after the towns in the USA where the disease was first identified) is a bacterial infection caused by Borrelia burgdorferi. "Lyme disease has been associated with the proinflammatory cytokines Interleukin-6, Interleukin-8, Interleukin-12, Interleukin-18 and interferon-gamma; the chemokines CXCL12, CXCL13 and CCL19 and increased levels of proinflammatory lipoproteins." (PMID 30149626, 2018).
malignant peripheral nerve sheath tumor (2 papers, 2017). Malignant peripheral nerve sheath tumor (MPNST) is a rare and often aggressive soft tissue sarcoma occurring in a wide range of anatomical sites. "Malignant peripheral nerve sheath tumors (MPNSTs) are aggressive, Schwann cell-derived neoplasms of the peripheral nervous system that have recently been shown to possess an autocrine CXCL12/CXCR4 signaling loop that promotes tumor cell proliferation and survival." (PMID 28055968, 2017).
MALT lymphoma (2 papers, 2015 to 2024). An indolent, extranodal type of non-Hodgkin lymphoma composed of small B-lymphocytes (centrocyte-like cells). "CXCL12 was predominantly observed in ducts and malignant B cells infiltrating the salivary glands of SS patients with MALT lymphoma; levels of CXCL12 were elevated in MALT lymphoma and isolated tumor cells." (PMID 38736890, 2024). "CXCL12/CXCR4 is an important chemokine for the aggregation of B cells into lymphoid follicles, and for the survival of malignant B cells in the salivary glands of mucosa-associated lymphoid tissue (MALT) lymphoma." (PMID 38736890, 2024). "Additionally, we found that CXCL12 and CXCR7—a CXCRL12 receptor—were upregulated during the progression of gastric MALT lymphomas to gastric eDLBCL, suggesting at least in part an implication of this signaling pathway in high-grade transformation of gastric MALT lymphomas." (PMID 25922601, 2015).
mammary adenocarcinoma (2 papers, 2011 to 2012). "Overexpression of CXCL12 in rat mammary adenocarcinoma cells increased in vivo invasion as well as microvessel and macrophage density." (PMID 22314082, 2012). "Using the rat mammary adenocarcinoma cell line MTLn3, we studied the effects of overexpression of CXCR4 and CXCR7 on CXCL12-induced chemotaxis and invasion, as well as in vivo motility, intravasation and metastasis formation." (PMID 22152016, 2011).
mastitis (2 papers, 2016 to 2025). Inflammation of breast tissue during lactation or postpartum due to an obstructed duct or infection. "The elevated inflammatory mediators that we found in this study, including the CXCL12 secreted by fibroblasts, may recruit neutrophils from blood into the alveolus in cooperation with inflammatory mediators secreted by other cells within the mammary gland during mastitis." (PMID 27272504, 2016).
medullary thyroid cancer (2 papers, 2021 to 2022). "Some complementary binding sites between miR-455-5p and CXCL12 have been found, and a significant inverse correlation has been detected as well, indicating that miR-455-5p might suppress medullary thyroid cancer growth and metastasis by targeting CXCL12/CXCR4 signaling pathway." (PMID 35647303, 2022).
neuropathic pain (2 papers, 2019 to 2021). Chronic pain caused by damage to nerve fibers. "Previous studies have demonstrated that the CXCL12/CXCR4 signaling axis is involved in the regulation of neuropathic pain (NP)." (PMID 30955244, 2019).
obliterative bronchiolitis (2 papers, 2015 to 2016). "Gene expression profiling of human and murine organizing pneumonia lesions showed in part comparable expression levels of pivotal genes, notably of TGFB1/Tgfb1, TIMP1/Timp1, TIMP2/Timp2, COL3A1/Col3a1, CXCL12/Cxcl12, MMP2/Mmp2 and IL6/Il6." (PMID 27282780, 2016).
ocular hypertension (2 papers, 2012 to 2024). Abnormally high intraocular pressure. "Furthermore, CXCL12 (C-X-C motif chemokine ligand 12) was the most central node in the network, and it was found that through an activation of the CXCR3 receptor, this chemokine promotes caspase activation, leading to apoptosis, and IOP elevation in a rat model of ocular hypertension." (PMID 39458974, 2024).
oral lichen planus (2 papers, 2020 to 2025). Oral lichen planus is a chronic inflammatory oral condition of unknown aetiology characterized by T-cell-mediated chronic immune response and abnormal epithelial keratinization cycle. "Notably, fibroblasts were the source of CXCL12 and interacted with the receptors of CXCR4 on T cells and NK cells, suggesting an important role of fibroblasts in recruiting immune cells in oral lichen planus." (PMID 40574847, 2025).
ovarian endometriosis (2 papers, 2019 to 2025). A non-neoplastic disorder characterized by the growth of endometrial tissue in the ovaries. "C-X-C motif chemokine ligand 12 (CXCL12) expression is elevated in ovarian endometriosis across all menstrual phases, playing a key role in promoting the proliferation, migration, and invasion of endometriotic cells." (PMID 41128555, 2025).
pancreatitis (2 papers, 2021 to 2024). Inflammation of the pancreas. "A previous study indicated that CXCL12/CXCR4 axis activation contributed to the progression of fibrosis during experimental pancreatitis." (PMID 38769308, 2024). "Reg4 ablation may increase CXCL12/CXCR4 axis activation during pancreatitis and thereby potentially lead to stimulated TGF-β/SMADs profibrotic signaling, and this might then activate pancreatic stellate cells." (PMID 38769308, 2024). "In this pancreatitis-related pain model, adult monocyte-derived macrophages migrate into the pancreatic tissue during the early stage of tissue damage or inflammation, and secrete HMGB1, which in turn activates RAGE and accelerates CXCL12/CXCR4 signaling, resulting in pancreatic pain." (PMID 34440650, 2021).
paroxysmal AF (2 papers, 2014 to 2022). "Previous study showed that CXCL12 was associated with anabatic atrial inflammation and fibrosis and its serum concentration varied among sinus rhythm, paroxysmal AF and persistent AF individuals." (PMID 35911532, 2022).
peripheral nerve injury (2 papers, 2018 to 2019). Injury to a peripheral nerve. "The results exhibited that pain sensitivity behavior is further exaggerated by CXCL12, suggesting either miR-23a alone or synergistic with CXCL12 participated in the regulation and generation of pain behavior following peripheral nerve injury." (PMID 29386025, 2018).
plasmacytoma (2 papers, 2015 to 2022). Plasmacytoma is a localized mass of neoplastic monoclonal plasma cells that represents approximately 5% of all plasma cell neoplasms. "The present study examines the functional role of RGS1 in regulating the CXCL12-mediated migration of RPMI 8226 plasmacytoma cells and plasmablasts." (PMID 25897806, 2015). "We found that augmented expression of RGS1 by lipopolysaccharide (LPS) suppressed the CXCL12-mediated migration and AKT activation in RPMI 8226 plasmacytoma cell line and plasmablasts generated from germinal center B (GC-B) cells." (PMID 25897806, 2015).
pneumococcal infection (2 papers, 2014 to 2021). Infections with bacteria of the species streptococcus pneumoniae. "We observed that MNC mice did not modify bone marrow CXCL12 expression in response to pneumococcal infection." (PMID 24691464, 2014).
polyp (2 papers, 2022 to 2023). A usually exophytic mass attached to the underlying tissue by a broad base or a thin stalk. "We show that loss of BMPR1A signaling in fibroblasts leads to polyp development through upregulation of CXCL12, driving epithelial cell proliferation and serrated polyp formation." (PMID 36326956, 2023). "Taken together, our study shows that fibroblasts with impaired BMP signaling upregulate CXCL12 expression, which is involved in serrated polyp development in the mouse intestine." (PMID 36326956, 2023). "Similarly, decrease in CCL5, CCL21 and CXCL12 chemokines are related with reduced cell adhesion which could enhance invasive character for polyp." (PMID 35486660, 2022).
psoriasis vulgaris (2 papers, 2021 to 2025). Plaque psoriasis is the most common presentation of psoriasis. "There was a significant decrease in CXCL12 expression in patients with psoriasis vulgaris after MTX treatment." (PMID 34440960, 2021). "PsA patients had significantly higher CXCL12 expression than patients with psoriasis vulgaris before treatment." (PMID 34440960, 2021).
psoriatic arthritis (2 papers, 2021 to 2024). Joint inflammation associated with psoriasis. "A study evaluated CXCL12 expression in PsO vulgaris and psoriatic arthritis (PsA) patients concerning disease activity and methotrexate (MTX) therapy, and findings showed significantly higher CXCL12 expression in PsA patients compared to PsO vulgaris patients before treatment but not after." (PMID 39070795, 2024).
pulmonary tuberculosis (2 papers, 2012 to 2023). A bacterial infection that affects the lungs and is caused by Mycobacterium tuberculosis. "Moreover, the levels of IP-10, CXCL11 and CXCL12 expression in LTB2 plasma were not significantly different from the levels found in pulmonary tuberculosis patients but were much higher than the levels detected in the healthy control group." (PMID 23028695, 2012).
retinoblastoma (2 papers, 2024 to 2025). A malignant tumor that originates in the nuclear layer of the retina. "Examining CXCL12’s correlation with specific cancer functions revealed positive links with inflammation, differentiation, and angiogenesis in retinoblastoma (RB) but negative correlations with DNA repair, DNA damage, and cell cycle." (PMID 40166682, 2025).
sarcopenia (2 papers, 2023 to 2024). Progressive decline in muscle mass due to aging which results in decreased functional capacity of muscles. "Thus, a possible mechanism of anti-myogenic action was hypothesized for CXCL12 in muscle stem cells and sarcopenia." (PMID 37297995, 2023).
SARS-CoV infection (2 papers, 2014 to 2021). "Most were upregulated such as PTGES, MIF, CCR7, CXCL6 and CXCL12, which encodes immune cytokines known to be transcriptionally upregulated during SARS-CoV infection." (PMID 34282405, 2021).
schizophrenia (2 papers, 2015 to 2019). A major psychotic disorder characterized by abnormalities in the perception or expression of reality. "Since both elevated CXCL10 and supressed CXCL12 compromise developing GABAergic interneurons, the results support maternal immune challenge contributing to schizophrenia-associated neurodevelopmental abnormalities." (PMID 30691477, 2019). "In addition, increased CXCL10 and decreased CXCL12 have been linked to impaired migration and function of cortical GABAergic interneurons and so may have particular relevance to schizophrenia risk." (PMID 30691477, 2019). "The expression of CXCL12 is decreased in olfactory neurons from sporadic cases with schizophrenia compared with normal controls." (PMID 25805966, 2015). "Previous studies also suggest a possible involvement of Cxcl12/Cxcr4 signaling in the neurodevelopmental disorders of GD17 MAM-treated animal model of schizophrenia." (PMID 25805966, 2015). "Cxcl12/Cxcr4 signaling might play pivotal roles in the pathogenesis of schizophrenia." (PMID 25805966, 2015).
serous carcinomas (2 papers, 2012 to 2022). "As the results for CXCL12 were independent of histological type, the lower number of serous carcinomas in this study should not affect the results." (PMID 22415233, 2012).
Splenomegaly (2 papers, 2012 to 2018). Abnormal increased size of the spleen. "Recently, JAK2 activation in MPL-mutant cells was found to support the CXCL12/CXCR4 pathway and activate downstream JAK-STAT, PI3K/AKT, and RAS/MAPK activation pathways, leading to the expansion of malignant clones, EMH, and splenomegaly in MF patients." (PMID 29562644, 2018). "Therefore, each mechanism, namely the CXCL12/CXCR4 pathway and low Gata1 expression, individually leads to the progression from EMH to splenomegaly in MF patients." (PMID 29562644, 2018).
thymic atrophy (2 papers, 2018 to 2021). "In this respect the absence of prominent changes in the thymic CXCL12 expression in AO rats exhibiting milder thymic atrophy did not seem to be surprising." (PMID 30086167, 2018).
urinary tract infection (2 papers, 2025). "CXCL12/SDF-1 is secreted by bladder epithelial cells during urinary tract infection, it regulates inflammation by NF-kB activation." (PMID 39822305, 2025).
uveitis (2 papers, 2017 to 2024). An inflammatory process affecting a part of or the entire uvea. "The intercellular communication analysis in our study among the retina cells predicted that Cxcl12-Cxcr4 was a significant ligand-receptor pair that was mainly sent by VECs and acted on immune cells, indicating the involvement of CXCR4 in ocular infiltration of immune cells during uveitis." (PMID 38684986, 2024). "Extension of this latter study with other chemokine polymorphisms and including another uveitis entity (VKH) did not reveal any new associations, although haplotype analysis did show that the haplotype TC of the CXCL12 gene including rs1801157 and rs2839693 shows a significant association with VKH." (PMID 28589131, 2017).
ventricular septal defect (2 papers, 2015 to 2022). The presence of a defect (opening) in the septum that separates the two ventricles of the heart. "Knockouts involving the CXCL12/CXCR4 axis are known to cause ventricular septal defects (VSDs), and developmental disruption of aortic arch, pulmonary artery, and coronary artery in animal models." (PMID 36148060, 2022).
visceral leishmaniasis (2 papers, 2008 to 2025). A severe form of leishmaniasis characterized by irregular bouts of fever, substantial weight loss, swelling of the spleen and liver, and anemia (which may be serious). "In chronic severe infections such as visceral leishmaniasis, WP disruption and late spleen plasmacytosis have been associated with extended plasma cell survival and splenic homing mediated by increased expression of BAFF, APRIL and CXCL12." (PMID 41210940, 2025).
abscesses (1 paper, 2024). "In addition, CXCL13+ FBs expressed multiple other chemokines (i.e., CXCL12, CCL19), which likely further contribute to the spatial localization of the B cell population at the periphery of actively inflamed abscesses and sinus tracts." (PMID 38051587, 2024).
acne (1 paper, 2024). An inflammatory process of the sebaceous glands which is characterized by comedones, nodules, papules and/or pustules on the skin. "It requires further study to determine whether the CXCL12/CXCR4 signaling pathway has a role in some rosacea and acne patients with itching and pain." (PMID 38321132, 2024).
acute respiratory distress syndrome (1 paper, 2025). Progressive and life-threatening pulmonary distress in the absence of an underlying pulmonary condition, usually following major trauma or surgery. "Consistent with this dual role, mesenchymal stem cells have been shown to alleviate TNF-α- and LPS-induced apoptosis by activating the CXCL12/CXCR4 axis, thereby reducing lung injury and fibrosis in experimental acute respiratory distress syndrome (ARDS) models." (PMID 41614816, 2025). "In the complex pathophysiology of acute lung injury/acute respiratory distress syndrome (ALI/ARDS), the CXCL12/CXCR4 signaling axis exerts context-dependent effects during both injury and repair, making it a compelling yet challenging therapeutic target." (PMID 41614816, 2025).
acute T cell leukemia (1 paper, 2025). "Migration assays showed that BKT300 significantly inhibited the migration of leukemic cancer cell lines, including AML U937 cells and acute T cell leukemia Jurkat cells, toward CXCL12." (PMID 40034437, 2025).
Adamantinomatous Craniopharyngioma (1 paper, 2020). A craniopharyngioma consisting of broad strands, cords and bridges of a multistratified squamous epithelium with peripheral palisading of nuclei. "For example, CXCL12 is generally overexpressed in adamantinomatous craniopharyngiomas, and the CXCL12/CXCR4 axis promotes tumor proliferation, migration, and invasion through PI3K/AKT signal pathway." (PMID 32381016, 2020).
allergic conjunctivitis (1 paper, 2013). "Because CXCL12 is a potent chemotactic factor for T and pre-B lymphocytes, plasma cells, and dendritic cells (DCs) and expression of SDF-1 (CXCL12) receptor (CXCR4) is also documented on eosinophils and mast cells - the two critical components in allergic conjunctivitis." (PMID 24024210, 2013).
ankylosing spondylitis (1 paper, 2024). An autoimmune chronic inflammatory disorder characterized by inflammation in the vertebral joints of the spine and sacroiliac joints. "Similarly, another member of the C-X-C motif ligand family, CXCL12, which was expressed in mesenchymal cells, was capable of inducing MSC migration and osteogenesis in OLF, and its expression in macrophages increased new bone formation in ankylosing spondylitis." (PMID 38880863, 2024).
ankylosis (1 paper, 2021). Fixation and immobility of a joint. "Among the up-regulated genes screened by PPI analysis in the ankylosis-induced side at day 4, a key gene, CXCL12, is worth noting." (PMID 34961493, 2021).
apical periodontitis (1 paper, 2019). "In apical periodontitis, CXCL12 proved to be the primary molecular signal responsible for the recruitment of mast cells into the periapical inflammatory infiltrate during lesion development." (PMID 31379856, 2019). "For example, we determined that CXCL12 levels increase significantly in apical periodontitis." (PMID 31379856, 2019).
autoimmune pancreatitis (1 paper, 2021). "In this study, we analyzed the serum levels of SDF-1/CXCL12 in IgG4-RD patients and the pancreatic expression of the chemokine in the subgroup of IgG4-RD with autoimmune pancreatitis." (PMID 34764871, 2021). "The SDF-1/CXCL12 expression was significantly higher in IgG4-RD with respect to normal pancreas tissue, comparable to those found in different disease groups including PDAC and in not-autoimmune pancreatitis." (PMID 34764871, 2021).
autonomic dysfunction (1 paper, 2024). "In addition, CXCL12 levels have been associated with nonmotor symptoms such as autonomic dysfunction, while α-syn levels in plasma neuronal exosomes have been linked to clinical stage, motor symptoms, and nonmotor symptoms." (PMID 38791346, 2024).
bronchiectasis (1 paper, 2020). Segmental, irreversible dilation of the bronchial tree resulting in the accumulation of secretions which leads to obstruction. "An abundance of C-X-C motif chemokine ligand 12 (CXCL12) and 13 (CXCL13) has been identified in lymphoid aggregates from the lungs of individuals with bronchiectasis and CF compared to the airway epithelium of control nonsmokers." (PMID 32397175, 2020).
calcific aortic valve disease (1 paper, 2025). "CXCL12 has also been shown to consistently be upregulated in individuals with calcific aortic valve disease." (PMID 40182431, 2025).